TLR2 (toll like receptor 2)
Diseases named in the same sentence as TLR2 in open-access papers (continued):
Sharing a sentence is not in itself a finding about the gene and the disease.
malaria (continued). "Mean expression of TLR‐2 and TLR‐4 was significantly lower in children with acute CM and SMA compared with healthy controls, while HLA‐DR and CD86 expression was significantly lower in all three malaria groups." (PMID 27027867, 2016). "Despite the down-modulation of TLR2 and TLR4, stimulation with TLR agonists increased the levels of IL-8 produced by neutrophils from malaria patients before (medium versus LPS, p = 0.0010 or Pam, p = 0.0024) and after treatment (medium vs LPS, p = 0.0002; or Pam, p = 0.0017)." (PMID 22745844, 2012). "Malaria-naïve adults experimentally infected with Pf had increased expression of TNF-α, IL-1β and IL-6 in response to a TLR4 ligand (LPS) and IL-6 and IL-10 in response to TLR2 + TLR1 ligand (Pam3Cys) on day 8 of the infection." (PMID 19691558, 2009). "Although these polymorphisms have not been studied in malaria case-control studies, TLR2 is potentially involved in the pathogenesis of malaria because of its putative role as a receptor for P. falciparum-derived GPI." (PMID 19317913, 2009). "Similar frequencies of TLR2, TLR4, TLR9, and MAL genetic polymorphisms in populations with different histories of malaria exposure suggest that these innate immune pathways have not been under strong selective pressure by malaria." (PMID 19317913, 2009). "A study in Thailand found that adults with both severe and mild malaria had a decreased number of TLR2 expressing cDCs circulating in the periphery and a lower surface expression of TLR9 on pDCs but an increase in the surface expression of TLR2 on cDCs compared with healthy controls." (PMID 32793231, 2020). "Thus, the observation that the expression of both TLR‐2 and TLR‐4 in convalescence of all malaria types was even lower than that observed in acute infection could be a result of such tolerance which could take longer than 30 days to dissipate." (PMID 27027867, 2016). "Adults with severe and mild malaria had increased expression of TLR2 and TLR4 on CD14+ monocytes and myeloid DCs and decreased expression of TLR9 on plasmacytoid DCs compared to adults with no history of malaria exposure." (PMID 19691558, 2009).
rosacea (43 papers, 2015 to 2025). A chronic erythematous skin disorder that affects the face. "In this study, we demonstrated that LL37, an antimicrobial peptide implicated in the pathogenesis of rosacea, directly binds to TLR2 on mast cells, triggering their degranulation." (PMID 41383625, 2025). "LL37-associated signaling pathways, particularly involving TLR2 and mTORC1, are critical in the pathogenesis of rosacea." (PMID 39351216, 2024). "Overall, cathelicidin LL-37 and its associated effectors play a major role in rosacea pathogenesis and future therapeutics will inevitably target players in its pathway such as mTORC1 and TLR2." (PMID 38193038, 2023). "Importantly, the TLR2/Myeloid differentiation factor-88 adaptor protein (MyD88)/NF-κB is implicated in rosacea pathogenesis, as suggested by elevated MyD88 levels in rosacea skin biopsies." (PMID 39351216, 2024). "However, whether the TLR2/KLK5/cathelicidin pathway in macrophages is involved in the mechanism underlying the efficacy of carvedilol in rosacea remains unknown." (PMID 34322115, 2021). "To date, the pathogenesis of rosacea remains largely unclear and is thougth to be associated with dysfunction in immune response, dysregulation of nervous and vascular system.Toll-like receptor 2 (TLR2), as a component of innate immunity, is highly expressed in keratinocytes of rosacea patients." (PMID 34993194, 2021). "TLR-2 activation additionally promotes the release of pro-inflammatory cytokines, chemokines, proteases, and pro-angiogenic factors, which are mediators associated with rosacea symptoms such as erythema, telangiectasia, or inflammation or a combination of these." (PMID 30631431, 2018). "The increased expression of type 2 Toll-like receptors (TLR2), cathelicidin, IL-37, and leukocyte activity in rosacea further suggests that microorganisms contribute to its pathogenesis." (PMID 40282951, 2025). "The production of cathelicidins is induced by the activation of TLR-2, receptors that are part of the innate immune system and are overexpressed on the skin of patients with rosacea." (PMID 40149947, 2025). "To elucidate the pivotal roles of TLR2 and S100A9 in the pathogenesis of rosacea, we established knockdown cell lines for TLR2 and S100A9." (PMID 39823143, 2025). "This microbial presence has the potential to activate Toll-like receptor 2 (TLR2) and consequently exacerbate the inflammatory processes characteristic of rosacea." (PMID 40149947, 2025). "TLR2 is a well-known immune receptor of mast cells, and its downstream adaptor protein, MyD88, is significantly upregulated in rosacea lesions." (PMID 41383625, 2025). "Our findings confirmed that LL37 induces mast cell activation through the TLR2/MyD88 signaling pathway, promoting the release of inflammatory mediators and chemokines that drive rosacea pathology." (PMID 41383625, 2025). "Our findings also reveal a significant upregulation of TLR2 and S100A9 expression in rosacea patients, which is consistent with previous research on TLR2 and S100A9." (PMID 39823143, 2025). "Compared with the healthy control group, the rosacea patient group showed significantly increased mRNA and protein levels of TLR2 and S100A9." (PMID 39823143, 2025). "Demodex, with its chitin exoskeleton, triggers inflammation by increasing TLR2 levels, and therefore becomes the major target of antimicrobial therapy for rosacea." (PMID 39136023, 2024). "Elevated levels of antimicrobial peptides, KLK5, TLR2, and MMPs have been observed in skin lesional of rosacea patients." (PMID 39692542, 2024). "TLR2 is also expressed in sensory neurons, and the TLR2 signaling pathway contributes to the mechanism of neurological dysfunction in rosacea." (PMID 39351216, 2024). "The role of LDL in inflammatory skin conditions can be explained through its interaction with Toll-like receptors (TLRs), particularly TLR-2, which is elevated in rosacea-affected skin." (PMID 39538162, 2024).
rosacea (continued). "Glucocorticoids can increase TLR2 expression in epidermal keratinocytes, potentially leading to glucocorticoid-induced rosacea-like dermatitis." (PMID 39351216, 2024). "TLR2, a primary pattern recognition receptor, is significantly overexpressed in rosacea patients’ keratinocytes, contributing to heightened skin sensitivity to various stimuli." (PMID 39351216, 2024). "On this issue, Demodex mites stimulate TLR-2 consequently increasing production of proinflammatory cytokines and playing a role in the continuum of rosacea pathogenesis." (PMID 38260914, 2023). "The recognition of microbial products by pattern recognition receptors, such as TLR2, which is overexpressed in rosacea, induce expression of cathelicidin by keratinocytes." (PMID 36633910, 2023). "In rosacea patients, TLR2 is overexpressed in KCs and infiltrating dermal cells at the site of skin lesions, leading to an overactive innate immune response." (PMID 37626650, 2023). "More specifically, epidermal keratinocytes in rosacea inflamed skin activates toll like receptors (TLR2) leading to the release of various cytokines." (PMID 36993812, 2023). "The epidermis of subjects affected by rosacea have higher TLR2 expression than healthy subjects, suggesting a mechanism for inflammatory signaling at a low threshold to external stimuli." (PMID 37623895, 2023). "SIRT7 downregulation in aging skin cells has been shown to downregulate TLR2 and inhibit NF-κB pathway activation, potentially explaining the decreased incidence or symptom relief of rosacea in the elderly population." (PMID 37626650, 2023). "SIRT7 is upregulated in skin samples of patients and in mouse models with rosacea and can regulate gene transcription of TLR2 which activates NF-kB." (PMID 36993812, 2023). "Demodex can directly activate TLR2 and, therefore, contribute themselves to the induction of an inflammatory response in rosacea." (PMID 36633910, 2023). "Meanwhile, EGCG treatment also reduced the expression of pro-inflammatory cytokines, including Il-6, Tlr-2, and Tnf-α in LL-37-induced rosacea-like lesions." (PMID 36937834, 2023). "Rosacea is characterized by immune dysfunction involving both innate and adaptive immunity, with alterations to the TLR2/KLK5/LL37 pathway being the most well-studied pathological mechanism." (PMID 37626650, 2023). "Macrophages also play a role in rosacea pathogenesis by expressing TLR2 and NLRP3, which activate inflammation." (PMID 37626650, 2023). "In this study, we demonstrated that carvedilol reduced TLR2-induced inflammation in macrophages, which are involved in the pathogenesis of rosacea in vivo and in vitro." (PMID 34322115, 2021). "Accordingly, in this study, we aimed to investigate the potential effects of carvedilol on TLR2 and inflammatory reactions related to macrophages in rosacea, both in vivo and in vitro." (PMID 34322115, 2021). "The TLR2/KLK5 pathway is also important for rosacea, as serine protease KLK5 activity and cathelicidin expression are highly up-regulated in this disease, promoting skin inflammation." (PMID 34322115, 2021). "Carvedilol is effective against rosacea, with inhibition of macrophage TLR2 expression as a novel anti-inflammatory mechanism." (PMID 34322115, 2021). "In conclusion, we present the first report that carvedilol can alleviate the inflammatory reaction in rosacea via the TLR2/KLK5/cathelicidin pathway in macrophages." (PMID 34322115, 2021). "The increased number of Demodex mites is likely to induce an inflammatory response in rosacea lesion through activation of the toll-like receptor 2 (TLR2) pathway." (PMID 33256158, 2020). "In rosacea patients, Demodex density appears higher than in healthy skin, which higher density activates downstream signaling pathway of TLR2, and increases the expression of inflammatory mediators." (PMID 33256158, 2020).
rosacea (continued). "Since CCE effectively acts on the expression of TLR2 and its downstream signaling pathway, it is expected that it offers potential as an anti-inflammatory material for rosacea." (PMID 33256158, 2020). "In mice, TLR-2-induced cathelicidin activation needs functional kallikrein-5 (KLK-5) protease activity for the formation of rosacea-like erythema and angiogenesis." (PMID 30631431, 2018). "An increase in Toll-like receptors-2 (TLR-2) expression, a family of PRRs, has been observed in inflammatory skin diseases such as rosacea." (PMID 29182532, 2017). "TLRs comprise a major subset of PRRs; among these, the expression of TLR-2 is increased in inflammatory skin disorders such as acne and rosacea." (PMID 27649161, 2016). "When TLR-2 is activated by external stimuli or triggering factors for rosacea, keratinocytes produce proinflammatory cytokines and chemokines." (PMID 27649161, 2016). "In turn, a genetic predisposition to carrying the rs3733631 polymorphic variant in the tachykinin receptor gene TACR3 was also observed in patients with rosacea; notably, this is near the TLR2 gene locus at 4q25." (PMID 27649161, 2016). "LL37 induces activation of the TLR2/JAK2 pathway in mast cells of rosacea-like mice." (PMID 41383625, 2025). "Specifically, the expression of FLT1 and TLR2 genes is significantly elevated in rosacea patients." (PMID 39823143, 2025). "Similarly, Yamasaki K’s study demonstrated an increased expression of TLR2 in rosacea patients, along with elevated levels of tumor necrosis factor-α (TNF-α), the main cytokine induced by TLR signaling." (PMID 40378103, 2025). "Our results support the notion that CHIT1 enzymatic activity may be an advantageous target for intervention in HDM–chitin–TLR2-mediated pathologies such as allergic asthma or the skin condition rosacea." (PMID 40098951, 2025). "The molecular mechanisms driving mast cell activation in rosacea remain poorly understood, though recent studies highlight the involvement of two key signaling pathways: the TLR2/MyD88 pathway and the Janus kinase/signal transducer and activator of transcription (JAK/STAT) pathway." (PMID 41383625, 2025). "In patients with rosacea, the overexpression of TLR2 may stimulate elevated pro-inflammatory cytokine production (IL-8, IL-1β, and TNF-α, etc.), exacerbating the inflammatory response." (PMID 41009424, 2025). "Overexpression of TLR2 in rosacea patients may stimulate elevated production of pro-inflammatory cytokines, such as IL-8, IL-1β, and TNF-α, exacerbating the inflammatory response." (PMID 41009424, 2025). "In addition, rosacea upregulates the expression level of TLR2, thereby increasing the secretion of KLK5 from keratinocytes." (PMID 39136023, 2024). "For example, activated TLR2 was reported to elevate rosacea-related kallikrein 5 (KLK5), subsequently producing the pro-inflammatory forms of antimicrobial peptide LL37, and LL37 interacts with TLR2 to activate mTOR signaling, eventually inducing the development of rosacea." (PMID 37780385, 2023). "Notably, TLR-2 is overexpressed in keratinocytes of rosacea patients enhancing skin sensitivity to external triggers because its stimulation activates an inflammatory cascade." (PMID 38260914, 2023). "LL-37 was administered to induce rosacea-like eruption in mice; however, topical treatment of benvitimod decreased redness scores, redness areas, the infiltration of dermal inflammatory cells, TLR2 expression, and chemokine expression." (PMID 36983027, 2023). "However, the understanding of TLR2 in rosacea is limited apart from these previous studies, so as other TLRs." (PMID 37780385, 2023). "Therefore, an exacerbated innate immune response is established in the skin of rosacea patients due to TLR-2 stimulation involving the production of the active form of the cathelicidin LL-37." (PMID 38260914, 2023).
rosacea (continued). "Additionally, endoplasmic reticulum (ER) stress plays a role in rosacea pathogenesis by stimulating cathelicidin production and increasing TLR2 expression." (PMID 37626650, 2023). "Toll-like receptor 2 (TLR2) levels are increased in rosacea patients and stimulate KLK5." (PMID 33670115, 2021). "Rosacea skin lesions exhibited more pronounced inflammatory cell infiltration than peripheral areas, with profound macrophage infiltration and inflammatory cytokines (TLR2, kallikrein 5, cathelicidin, TNF-α, and IL-1β)." (PMID 34322115, 2021). "Double-label immunofluorescence staining revealed that carvedilol could decrease levels of TLR2, which was mainly expressed on macrophages, in the skin of rosacea-like mice." (PMID 34322115, 2021). "Therefore, it is an important target in regulating the skin immune response by inhibiting the activation of TLR2 signaling in rosacea." (PMID 33256158, 2020). "Given that these proteins have been shown to stimulate TLR-2, this may explain the potential of this microbe as the immunogenic antigen involved in the TLR-2-mediated inflammatory cascade found in patients with rosacea." (PMID 27649161, 2016). "It is therefore reasonable to suppose that the polymorphism in TACR3 might be involved in the development of rosacea by enhancing the expression of TLR2." (PMID 27649161, 2016). "As the TLR-2 signaling pathways have the ability to mediate further neural dysregulation, the complex association between neural dysregulation and innate immunity in rosacea might therefore be explained by TLR-2." (PMID 27649161, 2016). "Therefore, vitamin D likely influences the TLR-2, KLK-5, and LL-37 associated pathway in rosacea and affects the subsequent proinflammatory cascades that can alter the immune system in these patients." (PMID 27649161, 2016). "Therefore, TLR2 and S100A9 may be associated with the observed skin thickening and accelerated damage repair processes in rosacea." (PMID 39823143, 2025). "Finally, the results in RAW 264.7 cells confirmed that the TLR2/KLK5/cathelicidin pathway could be enhanced in the rosacea-like inflammation mice model, whereas this was inhibited by pretreatment with carvedilol." (PMID 34322115, 2021). "TLR2, a membrane receptor expressed on the surface of certain cells and able to recognize foreign substances and transfer proper signals to the local cells, is aberrantly increased in the epidermis of rosacea patients, which parallels the hyperactivation of mTORC1 signaling." (PMID 33734592, 2021). "A recent study showed that Demodex mite extracts decreased TLR2 expression in cultured sebocytes, although this may be mite density dependent, as higher mite numbers appear to be associated with activation of TLR inflammatory pathways and rosacea pathogenesis." (PMID 32886659, 2020). "However, this increased TLR-2 expression cannot be observed in patients with other chronic inflammatory cutaneous diseases, such as psoriasis and atopic dermatitis, implying its special role in rosacea." (PMID 27649161, 2016). "Mechanistically, CBG inhibited the expression of cytokines, Vegfa, and Tlr2, as well as the activation of YAP/TAZ and JAK/STAT signaling pathways, which are known to be involved in rosacea pathogenesis." (PMID 40725084, 2025). "By elucidating the intricate interplay between LL37, TLR2, and JAK2/STAT3 signaling in mast cells, our findings provide novel mechanistic insights into rosacea pathogenesis and lay the groundwork for the development of targeted therapies." (PMID 41383625, 2025). "In rosacea, LL37 activates mTORC1 via Toll-like receptor 2 (TLR2), establishing a mTORC1-LL37-NF-κB positive feedback loop that drives cytokine/chemokine production and sustains inflammation." (PMID 40474977, 2025). "In summary, our study identifies the TLR2/MyD88/JAK2/STAT3 signaling pathway as a critical mediator of mast cell activation and degranulation in rosacea." (PMID 41383625, 2025).